TNF (tumor necrosis factor)
Diseases named in the same sentence as TNF in open-access papers (continued):
Sharing a sentence is not in itself a finding about the gene and the disease.
colon carcinoma (continued). "Although TNF-α mediates its action mainly through TNF-R1 activation, TNF-R2 has been linked to increased colon cancer cell growth and proliferation." (PMID 26896068, 2016). "Mechanism study using mouse colon cancer cells, colon 26 cells reveals that the cells treated with TNFα and IFNγ pass through early apoptosis to late apoptosis/secondary necrosis but not through primary necrosis." (PMID 27342639, 2016). "TNF-α is produced during the inflammatory response and can promote survival, attachment, and proliferation of metastatic colon cancer cells in a mouse model of lung metastasis depending on the activation of NF-κB by inflammation and cancer cells." (PMID 27323816, 2016). "Inflammatory cytokines such as IL-1α, IL-6 and TNFα are elevated in colon cancer and play important role in the mechanism of tumorigenesis." (PMID 26951793, 2016). "The role of TNF-α in promoting colon cancer metastasis was demonstrated via an experimental murine cancer metastasis model in which a colon adenocarcinoma cell line generated lung metastases." (PMID 26819599, 2016). "We previously reported the identification of a family of small molecules that induce mitotic arrest in colon cancer cells and increase their sensitivity to TNF and other death ligands." (PMID 27097159, 2016). "The increase in colon cancer cell migration capacity correlated with increased levels of peritoneal TNF-α and IL-10." (PMID 26819599, 2016). "It has been shown that knockdown of AEG-1 inhibits the ability to migrate and invade, whereas AEG-1 overexpression or treatment with TNF-α enhances migration and invasion in different cancer cell lines including colon cancer cell lines." (PMID 27835571, 2016). "Taken together, these results indicate that GEN-27 inhibits TNF-α-induced proliferation of human colon cancer cells through down-regulating the activity of p65-CDX2-β-catenin axis and reducing the expressions of the β-catenin target genes." (PMID 26910375, 2016). "In the literature, the Coiled-coil domain containing 3 (CCDC3) represses tumor necrosis factor-α/nuclear factor κB-induced endothelial inflammation and the CELF2 is associated with T-cell signaling and it is also a suppressor gene of colon cancer." (PMID 26635870, 2015). "Noteworthy, an increased expression of FGF-10, VEGFC, IL-10 and TNFα of AMSCs was found to be along with an elevated EMT gene expression of colon cancer cells in the co-culture model in this study." (PMID 26060426, 2015). "Aurora kinase pharmacological inhibition sensitized colon cancer cells to Tumor necrosis factor (TNF) and TNF-related apoptosis-inducing ligand (TRAIL)." (PMID 25987188, 2015). "TNFRs can be activated by TNF-α directly, by serum starvation in human colon carcinoma cells, or found in human airway smooth muscle cells which results in activation of JNK, p38, and ERK1/2." (PMID 24886705, 2014). "Tumor necrosis factor-α (TNF-α) has been suggested to be a putative tumor promoter gene, and autocrine of TNF-α expression has been found in colon cancer and ovarian cancer." (PMID 24676340, 2014). "Using various types of colon cancer cell lines, it was reported by us and others that the dual treatment with TNF-α and butyrate significantly increased apoptosis and decreased the differentiation induced by butyrate in HT-29 cells." (PMID 24876678, 2014). "Colon cancer cell-derived TNF-α plays an important role in promoting proliferation through autocrine mechanisms found in the tumor microenvironment." (PMID 24676340, 2014). "HSP70-TRAF2 suppressed the recruitment of RIP1 and inhibits NF-κB activation following stimulation by TNF-α, contributing to the apoptosis in human colon cancer cells." (PMID 24932290, 2014).
colon carcinoma (continued). "Further, the activated β-catenin can facilitate endosomal trafficking of internalised TNF-α to suppress caspase-8 activation in colon cancer cells." (PMID 24876678, 2014). "In conclusion, our results demonstrate for the first time that in colon cancer cells not only 1,25D3, but also the proinflammatory cytokines TNFα and IL-6 were able to induce the expression of CaSR." (PMID 24176760, 2014). "By contrast, colon cancer cell supernatants induced monocytes to produce more pro-inflammatory cytokines (i.e., IL-12 and TNF-α) and ROS." (PMID 23691510, 2013). "The PCT stimulators TNFα and IL-1β are actively involved in the pathogenesis of colon cancer and have been proposed as therapeutic targets for anti-cancer therapy." (PMID 23937962, 2013). "We previously found that TNFα also down-regulates CysLT2R while up-regulating CysLT1R in colon cancer cells, an observation that also highlights the importance of maintaining receptor balance in epithelial cells." (PMID 23829413, 2013). "Because IKK-α/β are upstream activator of IκB in the NF-κB signal pathway, we assessed the effect of GMF on TNF-α treated colon cancer cells." (PMID 24386633, 2013). "Conditioned media from TNF-α/IFN-treated HUVECs significantly increased the growth of human colon tumor xenografts in athymic mice 2.3-fold as compared to conditioned media from control-treated HUVECs (p = 0.0009)." (PMID 23056240, 2012). "Nevertheless, TNFα-mediated apoptosis sensitization function apparently overpowers TNFα-induced and NF-κB-mediated cell survival effect to result in an overall apoptosis sensitive phenotype in human colon carcinoma." (PMID 21264227, 2011). "TNFα and IFN-γ cooperate to repress Bcl-xL expression, whereas TNFα represses Survivin expression in the metastatic colon carcinoma cells." (PMID 21264227, 2011). "Exposure of human colon carcinoma cells to TNFα rapidly activated NF-κB, and blocking NF-κB activation significantly increased human colon carcinoma cells to TRAIL-induced apoptosis, suggesting that NF-κB does counteract with TRAIL-induced apoptosis." (PMID 21264227, 2011). "Taken together, our data suggest that IFN-γ and TNFα sensitize human colon carcinoma cells to TRAIL-induced apoptosis also through modulating caspase 8 activation." (PMID 21264227, 2011). "In conclusion, plumbagininduces apoptosis in colonic cancer cells through TNF-α mediated pathwaydepending on expression of COX-2 expression." (PMID 21559086, 2011). "TNF-α induced NF-κB activation, as a key event in inflammatory signaling, was analyzed in the human colon carcinoma cell line CaCo2." (PMID 21152327, 2010). "In preliminary studies we found significantly higher levels of both pro–inflammatory cytokines (TNF–alpha, IL–6, IL–8) and anti–inflammatory cytokine IL–10 in colon cancer patients as compared to healthy subjects (unpublished observations)." (PMID 21254741, 2010). "Bates and Mercurio demonstrated that TGFβ1-induced EMT is accelerated dramatically by the presence of activated macrophages, identified TNF as the critical factor produced by macrophages that accelerates the EMT in a model of colon cancer." (PMID 20047688, 2010). "Such a finding was initially based on an animal model with colon cancer, in which injection of LPS enhanced the development of lung metastasis dependent on TNF-α production by host cells." (PMID 20699000, 2010). "It was recently suggested in a mice model of colon carcinoma, that potentiation of the anticancer activity of bortezomib by combination with TNF-α resulted from reduced expression of proteasome subunits and inhibition of Hsp27." (PMID 18021420, 2007). "JAK2 has been shown to be activated in response to a wide variety of stimuli and AG-490 to block induced NOS2 expression in IL-1β/TNFα/IFNγ-stimulated human epithelial-like colon carcinoma DLD-1 cells and in IFNγ/LPS stimulated RAW cells." (PMID 18036230, 2007).
colon carcinoma (continued). "EMMPRIN could enhance TNFα secretion from monocytes co-cultured with activated platelets and TGFβ was shown to increase TNFα levels in co-cultures of colon carcinoma cells with normal colon epithelial cells, myofibroblasts, and endothelial cells." (PMID 41462963, 2025). "Of them, 10 aging-related CpG sites were mapped to 6 genes (i.e., TNF, BICC1, TBX3, SUCNR1, NCF2, DIP2B), and the altered methylation of cg03037030 located in TNF was associated with the risk of CRC, colon cancer, and rectal cancer, with consistent effect direction." (PMID 41197401, 2025). "TNF-α plays a critical and complex role in colon cancer progression." (PMID 40558596, 2025). "It has also been reported that the tumor necrosis factor a (TNFα) triggers abnormal AID expression in certain inflammation-related cancers such as helicobacter pylori-associated gastric cancer and colitis-associated colon cancers." (PMID 41373684, 2025). "Besides the well-known pro-inflammatory IL-6 cytokine, TNF-α was found to promote proliferation and inhibit apoptosis in colon cancer cells by activating STAT3." (PMID 39641861, 2025). "TNFα has context-dependent effects on human colon cancer cells." (PMID 40558596, 2025). "In colon cancer, TNF-α stimulates transcription factors like nuclear factor kappa-light-chain-enhancer of activated B cells (NF-κB) and signal transducer and activator of transcription 3 (STAT3), which promote angiogenesis, cell proliferation, survival, and immune evasion." (PMID 40558596, 2025). "TNF-α can activate anti-tumor immune responses, yet it can also facilitate immune suppression within the tumor microenvironment, adding to the ongoing controversy surrounding its overall impact on colon cancer pathophysiology." (PMID 40558596, 2025). "In addition, P2RY6 protects colon cancer cells from TNF-α-induced apoptosis by activating AKT-mediated phosphorylation of the X-linked inhibitor of apoptosis protein (XIAP)." (PMID 41383622, 2025). "Our results indicate a relationship between TNF-α and AmotL2 expression, either in healthy areas of the colon from patients suffering from colon cancer resected previous to OxPt chemotherapy or in healthy areas of resected colon from patients after chemotherapy." (PMID 39335466, 2024). "CXCL10 has been shown to synergize with TNF-α (also present in MPE) to induce EMT in colon cancer." (PMID 39114667, 2024). "TNFα plays a role in colon cancer angiogenesis through the TNFα/NF-κB signaling pathway." (PMID 38844562, 2024). "In vitro studies revealed that butyrate and propionate were more potent than acetate in suppressing lipopolysaccharide (LPS)-induced TNFα production by neutrophils and inhibiting TNFα-mediated nuclear factor kappa-B (NF-κB) activation in a human colon cancer cell line." (PMID 38255916, 2024). "Furthermore, there is a study in the literature in which high TNF-α levels in colon cancer resulted in oxaliplatin resistance, which was prevented by infliximab." (PMID 38776022, 2024). "Interestingly, qualitative but not quantitative KD-induced changes in NK cells, featuring higher IFN-γ and TNF-α production by NK cells, have been observed in mouse models of glioma and colon cancer." (PMID 39537934, 2024). "Small molecule RNF31 inhibitors sensitize colon cancer organoids to TNF-mediated death." (PMID 37117215, 2023). "TNF-α has been found to play an important role in colon cancer research." (PMID 37538184, 2023). "Recent studies have shown that tumor necrosis factor a (TNFα) triggers abnormal AID expression via nuclear factor-κB (NF-κB) in certain inflammation-related cancers such as helicobacter pylori-associated gastric cancer and colitis-associated colon cancers." (PMID 37600817, 2023). "In CRC, the actual TNFα concentration in colon cancer tissue is reportedly as low as 150 pg/mL." (PMID 36996146, 2023). "Therefore, the direct inhibition of TNF-α by infliximab reduced colon cancer formation in the AOM/DSS/Ab mice." (PMID 37185713, 2023).
colon carcinoma (continued). "Similarly, PANoptosis can be driven by the combination of tumor necrosis factor (TNF) and IFNγ, and human colon cancer cells deficient in IRF1 are resistant to TNF plus IFNγ-induced PANoptosis." (PMID 37557956, 2023). "We aimed to determine whether the anti TNF-α Ab induces colon cancer development in vitro and in vivo, and to identify the genes involved in colitis-associated cancer." (PMID 37185713, 2023). "In addition, in the presence of effector cells (macrophages) or active complements, anti-TNF treatment with infliximab markedly suppressed the survival of colon cancer cells." (PMID 36923938, 2023). "Chenodeoxycholic acid and ursodeoxycholic acid inhibit IL-1, IL-6, and TNF-α at certain concentrations by inhibiting the activity of monocytes, while lithocholic acid downregulates NF-κB activity via vitamin D receptors in colon cancer cells." (PMID 36819995, 2023). "Phytate modulates the transcription of genes encoding TNF and its receptors (TNFRI and TNFRII) in human colon cancer cells line (Caco-2), where the transcription of TNFRI is increased and of TNF and TNFRII reduced, showing an anti-inflammatory and antitumor role of phytate." (PMID 37937602, 2023). "Furthermore, enhanced cancer cells invasion and the metastasis ability of HCT-116 human colon cancer cells exposed to low doses of TNF-α has been demonstrated in a recent study." (PMID 37760840, 2023). "Compared with fentanyl, remifentanil administration during laparoscopic surgery for colon cancer was reported to significantly alleviate inflammatory responses with reduced secretion of serum TNF-α, improve oxidative stress indices, and decrease the frequency of adverse reactions." (PMID 36765695, 2023). "Increased serum levels of TGF-β and TNF-α, detected in the patients with right-sided colon cancer, could predict adverse outcome with respect to the patients with left-sided colon cancer." (PMID 37762927, 2023). "This may indicate that D. maritima bulb extract induces apoptosis in colon cancer cells through the TNF-α, IL-6, and caspase-8 activation pathways." (PMID 36770882, 2023). "Furthermore, an in vitro study also demonstrated that the addition of TNF-α, IL-1β, and IL-6 factors to the conditioned medium of activated macrophages significantly triggered the proliferation and immigration of human colon carcinoma cells." (PMID 36559282, 2022). "For instance, RNA-seq dataset reanalysis of colon tumours demonstrated that TAMs, in which NO signalling was increased, also exhibited enhanced inflammatory pathway activation, including TNF-α and IL-6 signalling, when compared to macrophages from normal areas." (PMID 35660630, 2022). "Moreover, one of the major lipid constituents in royal jelly is 10-hydroxy-2-decenoic acid, which was said to exert anti-inflammatory consequences in colon cancer cells passing through inhibiting NF-κB, which further inhibited the release of TNF-α." (PMID 35624893, 2022). "In addition, TNF-α-deficient mice with CAC showed a reduction in mucosal damage after AOM/DSS treatment, followed by alleviation of colonic tumors." (PMID 36295848, 2022). "In addition, imatinib can also halt the proliferation of colonic tumor cells and is involved generally in inflammatory pathways, through its inhibition of TNF-alpha production." (PMID 35246229, 2022). "The activation of CYP1A effectively controls the pro-oxidants and oxidative stress in colon cancer cells further, suppressing the proinflammatory cytokines IL-1β and TNF-α, which favors the deactivation of malignant cell apoptosis inhibitor NF-kB in colon cancer cells." (PMID 36430918, 2022). "Similarly, a strong decrease in tumor progression was exhibited when TNF-α was blocked in mice induced with colon tumors by azoxymethane (AOM) and dextran sulfate sodium (DSS)." (PMID 35954156, 2022).
colon carcinoma (continued). "Likewise, we detected the colon cancer prognostic biomarker CXCL8 and its associated pro-inflammatory cytokines (IL1-β, TNF-α, IFN-γ and IL-6) in the serum of mice in each group." (PMID 35922850, 2022). "SMYD2 in colon tumor cells inhibits TNF-induced apoptosis and necroptosis." (PMID 35022391, 2022). "Additionally, HAMA from WH has demonstrated specific cytotoxic activity against colon cancer cells and anti-TNF activity." (PMID 35571953, 2022). "Specifically, these shared pathways with IBD were linked to inflammation (TNF, IL-1A, IL-1B, NFkB, IL-6) and growth (TREM1, TGFB1), while other pathways shared with colon cancer were associated with colorectal metastatic signaling, growth (TREM1, NFkB and HMGB1) and inflammation (IL-8, IL-6)." (PMID 35323693, 2022). "Colloidal gold conjugated with PEG and TNF showed a specific accumulation in mouse colon tumors (MC-38) to a greater extent than free TNF, and was more effective in reducing tumor volume at a lower dose than native TNF, and also exhibited minimal systemic toxicity." (PMID 35591689, 2022). "On a molecular level, SMYD2 deficiency sensitized colonic tumor cells to TNF-induced apoptosis and necroptosis without affecting cell proliferation." (PMID 35022391, 2022). "IL-17 and TNF-α up-regulate PD-L1 expression in human prostate and colon cancer." (PMID 35902909, 2022). "TNF-α promotes PD-L1 expression in human prostate and colon cancer cells." (PMID 36479088, 2022). "HSPB1 was shown to increase the degradation of ubiquitinated proteins in response to stress stimuli triggered by TNF-α when interacting with the 26S portion of the proteasome in human leukemia (U937), murine embryogenic fibroblast, and rat colon carcinoma cells." (PMID 34571827, 2021). "The results showed that the targets of ursolic acid in treating colon cancer mainly included the TNF signaling pathway; the AGE-RAGE signaling pathway in diabetic complications, human cancer virus infections, hepatitis B, and Kaposi sarcoma-associated virus infections; and IL-17 signaling pathways." (PMID 34194533, 2021). "In this study, we hypothesized that tumour necrosis factor-α (TNF-α), a key mediator of inflammation, modulates BaP- and PhIP-induced DNA damage in colon cancer epithelial cells." (PMID 33961948, 2021). "In order to understand which of these parameters is a better marker to differentiate the presence of metastases and high-grade in colon cancer patients, we found that only NF-κBand TNF-α gave significant results when ROC curve, the cut-off values, and risk analysis were performed." (PMID 33776564, 2021). "Furthermore, flow cytometry cell death assays based on Annexin V-FITC/PI staining revealed that increased Prx (I, II, III) expression resulted in a decline in colon cancer cell death after Srx depletion and TNFα/CHX treatment." (PMID 34798428, 2021). "For instance, TNF is expressed at the invasive front of colon cancers." (PMID 33917839, 2021). "TNFα along with TGFβ triggers EMT in colon cancer cells through activation of Snail1, claudin-1, and the NOD-like receptor family, pyrin domain containing 3 (NLRP3), and activates EMT in renal cell carcinoma through overexpression of chemokine receptors such as CXCR2 and CXCR3." (PMID 34220337, 2021). "In addition, TNF-α increased the expression of PD-L1 in colon cancer, leading to tumor immunosuppression." (PMID 34194533, 2021). "Inflammatory mediators IL-1β, TNF-α, and IL-6 are increased at the early onset of colorectal cancer, and inhibiting the production of these cytokines can be an effective strategy to prevent colon cancer development." (PMID 34684488, 2021). "However, they observed that both TNFα and IL-17 upregulated PD-L1 via NF-κB but rather individually than cooperatively in human prostate and colon cancer cells." (PMID 32486375, 2020).